MUTYH (mutY DNA glycosylase)
Diseases named in the same sentence as MUTYH in open-access papers (continued):
Sharing a sentence is not in itself a finding about the gene and the disease.
cancer (continued). "Additionally, we assessed the allele frequencies of the genes in the gnomAD non-cancer cohort (n = 134 187), which showed significant differences in BRCA1, BRCA2, CHEK2, MUTYH, MSH6, POLE, and ERCC3 genes in comparison to our non-HBOC groups." (PMID 39148954, 2024). "However, on the basis of the results of this study (an absence of MSI-high in 35 analyzed carcinomas), we conclude that the MSI pathway is not an important pathway in the development of MUTYH associated tumours." (PMID 19527492, 2009). "During the last three years also deep sequencing data on solid cancer unveiled unexpected germline gene aberrations in neuroendocrine neoplasia (e.g., MUTYH, CHEK2, and BRCA2 genes in pancreas NEN) together with a substantial absence of known cancer drivers." (PMID 32869113, 2021).
tumor (101 papers, 2009 to 2026). "It aligns with a shared pathogenic somatic variant and loss of heterozygosity in MUTYH (NM_001128425.2:c.1213C > T; p.Pro405Leu) in this tumour." (PMID 39020404, 2024). "The characteristic C‐to‐A base substitutions in MUTYH‐deficient tumours increase the formation of stop codons, contributing to the inactivation of tumour suppressor genes." (PMID 36808802, 2023). "In pancreatic neuroendocrine tumours (PanNETs), we discovered four patients with tumours clustering in MuAt feature space to harbour germline mutations in MUTYH (p.Tyr176Cys, two patients; p.Pro292Leu; c.924+3A>C)." (PMID 37420249, 2023). "MuAt also clustered together a group of four pancreatic neuroendocrine tumours harbouring germline mutations of MUTYH with loss-of-heterozygosity in the tumours, demonstrating the ability of MuAt to identify tumours with similar germline DNA repair defects." (PMID 37420249, 2023). "In PC‐D, LOH for a heterozygous germline mutation in MUTYH was observed in the tumour and associated with the characteristic SBS18, supported by evidence of increased oxidative DNA damage on immunohistochemistry." (PMID 36808802, 2023). "The absence of germline mutation (or epimutation) detected in MMR genes (and in MUTYH or POLE) should lead to a further tumor analysis to look for biallelic somatic MMR gene mutations." (PMID 33530449, 2021). "In fact, Signature. has been consistently reported in tumours carrying a germline bi-allelic mutation in the MUTYH gene, encoding a DNA glycosylase involved in the repair of oxidative DNA damage." (PMID 33168834, 2020). "Subsequent work revealed that these mutations not only compromise the bacterial mutY, but also caused a decrease in the activity of human MUTYH for excision of A opposite 8-oxo-G, which nicely correlated with the tumor phenotype." (PMID 23450852, 2013). "Comparative analysis with mismatch repair (MMR)–deficient tumors demonstrated that patients carrying MUTYH mutations exhibited microsatellite stability, relatively low tumor mutation burden (TMB), and an immunosuppressive microenvironment, indicating difficulties in benefiting from immunotherapy." (PMID 40469416, 2025). "Genetic testing of the excised tumor revealed a MUTYH gene mutation and a BARD1 (BRCA1-associated RING domain 1) gene mutation of unknown significance." (PMID 39233942, 2024). "We next assessed DNMs from parents with mono-allelic (heterozygous) or bi-allelic (homozygous or compound heterozygous) germline MUTYH mutations, noting that only the latter have been reliably linked to functional base excision repair deficiency and to a tumour phenotype in humans." (PMID 37336879, 2023). "Moreover, a concomitant study on PanNETs demonstrated the presence of germline MUTYH mutations and defective DNA repair also in this tumor type." (PMID 30657883, 2019). "Known founder mutations were identified in tumor profiling reports of seven unique cases (8.4%; 7/83), including CHEK2 (I157T, n = 1), HOXB13 (G84E, n = 2) and MUTYH (G368D, n = 2 and Y151C, n = 2)." (PMID 39885482, 2025). "Unique molecular characteristics have been described in neoplasms from defective DNA repair-related polyposis involving the MUTYH, NTHL1, MBD4, MSH3, POLE and POLD1 genes and the MMR genes in CMMRD." (PMID 40237887, 2025). "After that, a group of primary tumor cells acquired six additional mutations (in genes AKT1, BCL9L, B2M, FBXW7, MUTYH, RSPO2)." (PMID 38685065, 2024). "In Group 2, four out of 174 participants with neoplasms carried variants in BRCA2 (rs768580992, review status “reviewed by expert panel”) and MUTYH (rs36053993, rs36053993, and rs34612342; review status “multiple submitters”)." (PMID 39301547, 2024).
tumor (continued). "Relative gene expressions of both MUTYH and hOGG1 were significantly lower in tumor tissue that in adjacent mucosa, so was hOGG1 protein expression determined by IHC." (PMID 35628513, 2022). "Similar tendency of downregulated MUTYH and hOGG1 in tumor tissues was also found on a group of 49 sporadic CRC patients from Brazil." (PMID 35628513, 2022). "In this tumor, ten somatic mutations were detected with high reconstruction error (45.8%) and SBS18/36 TMS of 24.9%—which suggests <1% likelihood of the tumor being related to biallelic MUTYH inactivation." (PMID 35668106, 2022). "Relative gene expressions of MUTYH and hOGG1 glycosylases significantly correlated in both tumor (rho = 0.599, p ˂ 0.001) and adjacent mucosa (rho = 0.638, p ˂ 0.001) tissues." (PMID 35628513, 2022). "The pathogenic germline variants in mCRPC, recurrent germline and somatic variants, and hotspot positions in different tumour types were mapped onto ATM, BRCA1, BRCA2, and MUTYH available structures, in order to find 3D-clusters of variants." (PMID 34253785, 2021). "Only one MUTYH+/+ mouse fed an HFHC diet developed an extrahepatic tumor, this being in the small intestine." (PMID 33574380, 2021). "The MUTYH germline variant enriched by amplification in the tumor of CABR10 (c.1178G>A) is a hotspot pathogenic variant and has previously been shown to alter MUTYH function." (PMID 32295625, 2020). "The level of MUTYH gene expression is related to tumor location, tumor size, degree of cell differentiation and depth of invasion to the intestinal wall, angiolymphatic infiltration, and lymph node involvement." (PMID 31724937, 2019). "MUTYH-dependent formation of toxic secondary DNA lesions would function as a potential anti-tumour barrier." (PMID 25638157, 2015). "Although HUWE1 has been shown to mediate the turnover of MUTYH in tumor cells, its role in AKI remains unknown." (PMID 39921445, 2025). "As proven in the present study, the list of genes from the 44-gene panel more frequently mutated in BOT compared to the other tumor groups (FANCB, SEM1, FANCA, BRCA2, CHEK2, MUTYH, RAD50) was much longer than analogically altered genes in the hot-spot panel (KRAS only)." (PMID 39456660, 2024). "The defective MMR protein expression in tumor tissue can be attributable to germline or somatic mutation in another DNA repair or replication-associated gene, such as BRAF, POLE/POLD1, or less frequently, MUTYH." (PMID 38297350, 2024). "In addition, the patient’s tumor had mutations in genes that are associated with genetic instability, including a CHEK2 mutation and VUSs in MSH3, and MUTYH." (PMID 37202426, 2023). "Interestingly, a good correlation between expressions of hOGG1 and MUTYH genes was found in both tumor tissue and adjacent mucosa." (PMID 35628513, 2022). "Occasionally, defective MMR protein expression in tumor tissue can be secondary to germline or somatic mutation in another DNA repair or replication-associated gene, such as POLD1/E or less frequently, MUTYH." (PMID 32660107, 2020). "In the tumor sample, no additional somatic mutations of MUTYH or loss of heterozygosity at its genomic locus were observed." (PMID 33024574, 2020). "Moreover, both AXIN2 and MUTYH are expressed in N14-77 samples at a level resembling other canine intestinal normal and tumor samples." (PMID 30018743, 2018). "Furthermore, previous analyses of gene copy number alterations in SI-NETs showed that chromosome 1p (where MUTYH is located) is rarely affected by tumor-specific deletions, which speaks against a frequent biallelic inactivation of this gene." (PMID 28634180, 2017).
tumor (continued). "One study reported that other tumor suppressors resulting in MSS tumors, such as MutYH, PolD, PolE, and NTHL1, might be associated with the pathogenesis of CRC in addition to APC gene mutations." (PMID 29237421, 2017). "An accumulation of 8-oxoG and upregulation of MUTYH were observed in tumor tissues." (PMID 26576226, 2015). "Oka and coworkers (2008) demonstrated that the knockdown of MUTYH results in escaping from both types of pathways and proposed a tumor suppressor role of MUTYH due to its capability to induce death of pre-cancerous cells that have accumulated high levels of 8-oxoG in nuclear or in mitochondrial DNA." (PMID 22876359, 2012). "For the heterozygous germline variants in other DNA damage repair genes, MUTYH and NTHL1, the mutational signature analysis indicates possible involvement in the etiology of EC, but only when there were indications of the germline variant being enriched in the tumor." (PMID 33917078, 2021). "Finally, no cases with the germline pathogenic MUTYH variant (c.1187G>A, p.Gly396Asp) showed evidence of variant enrichment in the tumor nor presence of Signature 18, associated with MUTYH inactivation." (PMID 33917078, 2021). "MUTYH is a DNA repair gene, whose alteration would be expected to increase the number of tumor-specific mutations but the researchers did not indicate whether the mutation rate was lower in I-NETs lacking this MUTYH allele." (PMID 34680217, 2021). "This tumor was however not characterized by an overaccumulation of G:C>T:A transversions (20%) or signature 18 contribution (reflecting 8-oxoguanine-related mutagenesis and MUTYH deficiency)." (PMID 32295625, 2020). "Tumor data may also inform possible roles for VUS or autosomal recessive gene variants in pathogenesis, recently demonstrated in a patient with biallelic variants in MUTYH (p.Gly286Glu and p.Ser346Ser) with tumor evidence supporting global deficiency in base excision repair." (PMID 33134827, 2020). "This study also showed that combined ko of MUTYH with OGG1 led to a decrease in life span and increased tumor formation for double ko mice compared to single ko." (PMID 23450852, 2013). "In contrast, variants in STK11, PMS2, MUTYH, and RB1 were primarily classified as VUS and did not demonstrate an apparent relationship with tumor aggressiveness." (PMID 41595443, 2025). "However, due to the unavailability of tumor specimens from the relevant patients, we have not been able to carefully study tumors from all patients for deletions on 1p (where MUTYH is located), with an aim to uncover the mechanism of inactivation of the other allele of the MUTYH gene." (PMID 28634180, 2017). "In addition, somatic mosaicism of MMR gene pathogenic variants or germline pathogenic variants in non-MMR genes, including POLE, POLD1 or MUTYH that somatically inactivate one of the MMR genes, are rare causes of tumor dMMR." (PMID 37101184, 2023). "Interestingly, only 3 somatic substitutions c.38C>T (p.A13V) [rs587780747], c.141G>A (p.K47K) and c.695C>T (p.T232I) in MUTYH gene (NM_001128425) have been detected in the tumor tissue; however, with no unambiguous pathological effect on the protein." (PMID 35628513, 2022). "In addition, the genetic marker for MAP‐tumors (KRAS c.34G > T) was absent in this tumor, which points toward retained MUTYH repair activity." (PMID 32615015, 2020). "Modifications in DNA methylation pattern and also enrichment of methylated histone signs in the promoter regions of some certain genes like MUTYH, KLF4/6 and WNT1 in different signaling pathways could be a notable key contributors to the upregulation of tumor initiation in CRC." (PMID 31724937, 2019).
tumor (continued). "Although OGG1-BER protects the genome integrity by repairing the lesion or eliminating cells with malignant potential and its overexpression improves H2O2-induced cell death, in the case of TPC-1 cells, the lack of MUTYH gene expression could favor the maintenance of tumor phenotype loop." (PMID 35269445, 2022).
adenocarcinoma (6 papers, 2009 to 2025). A common cancer characterized by the presence of malignant glandular cells. "KRAS, BRAF, STK11/KEAP1, MUTYH/RET, and RBM10/MET-associated modules showed the opposite trend, having significantly higher frequencies of adenocarcinoma cases as genomic alterations increased (P ≤ 0.02)." (PMID 39664186, 2024). "Previously, the MutY homolog (MUTYH)-null mice have been reported to have a higher susceptibility to intestinal adenoma and adenocarcinoma." (PMID 28820464, 2017).
autosomal recessive disease (3 papers, 2018 to 2024). Autosomal recessive form of disease. "Particularly, MUTYH-associated polyposis (MAP) is an autosomal recessive inherited disorder caused by germline mutation of both alleles of the MUTYH gene (also known as MYH gene), encoding a DNA glycosylase involved in the base excision repair of the mismatches caused by oxidative DNA damage." (PMID 29652830, 2018).
infection (3 papers, 2019 to 2022). The state of being infected such as from the introduction of a foreign agent such as serum, vaccine, antigenic substance or organism. "The protein levels of NTHL1, MUTYH, FEN1, RAD51, POLD1, and LIG1 were observed to be decreased, during the infection, in a CagA- and phospho-CagA-related manner in both cell lines." (PMID 33339161, 2020).
neurodegenerative disease (3 papers, 2012 to 2021). A disorder of the central nervous system characterized by gradual and progressive loss of neural tissue and neurologic function. "Though not much is known about the detailed role of MUTYH in the brain DDR, alterations in the MUTYH homeostasis have been associated with various neurodegenerative diseases, such as PD." (PMID 23203191, 2012). "Taken together, the evidences point at a potentially important role of MUTYH in the pathogenesis of neurodegenerative diseases such as PD and stroke, as well as age-dependent retinal degeneration and equine cerebellar abiotrophy." (PMID 23203191, 2012).
CNS tumors (2 papers, 2022 to 2025). "A thorough PubMed database search identified nine additional cases of germline MUTYH mutations in CNS tumors." (PMID 40469416, 2025). "Our findings suggested a potential association between germline MUTYH mutations and CNS tumor susceptibility." (PMID 40469416, 2025). "The risks of CNS tumors for MUTYH mutation carriers are not well defined." (PMID 40469416, 2025).
neurological disease (2 papers, 2013 to 2020). "Interestingly, MUTYH has been suggested to be involved in the pathogenesis of equine cerebellar abiotrophy, a neurological disease found in Arabian horses, as indicated by a SNP in the GATA2 binding region of the MUTYH promoter." (PMID 23450852, 2013).
hematological malignancies (1 paper, 2022). "In addition to the genes known to predispose to hematological malignancies, patients harbored several interesting variants in genes primarily associated with an increased risk for solid tumors (MUTYH, PMS2, and CHEK2)." (PMID 35739278, 2022).
MUTYH also shares sentences with these, for which no sentence is quoted: Cowden syndrome (7 papers); genetic disorders (5); attenuated familial adenomatous polyposis (4); colon polyps (4); Peutz-Jeghers syndrome (4); Alzheimer disease (3); hereditary non-polyposis colorectal cancer (3); medulloblastoma (3); polyp (3); anemia (2); cervical dysplasia (2); familial breast cancer (2); gastrointestinal tumors (2); gynecologic cancer (2); hepatocellular carcinoma (2); Hereditary Diffuse Gastric Cancer (2); hereditary mixed polyposis syndrome (2); leukemia (2); liver cancer (2); medullary thyroid cancer (2); osteosarcoma (2); acral melanoma (1); acute lymphoblastic leukemia (1); Arrhythmogenic right ventricular dysplasia (1); asthma (1); ataxia telangiectasia (1); autism (1); autosomal dominant disease (1); Bloom syndrome (1); Bowel cancer (1).
A further 73 diseases each share a sentence with MUTYH in 1 paper.